TNF (tumor necrosis factor)
Diseases named in the same sentence as TNF in open-access papers (continued):
Sharing a sentence is not in itself a finding about the gene and the disease.
periodontitis (continued). "The elevated levels of TNF-α observed in patients with periodontitis corroborate its well-established role in periodontal inflammation, bone resorption, and connective tissue destruction." (PMID 40542868, 2025). "Periodontitis induces a local and systemic inflammatory response, with an increase in pro-inflammatory cytokines such as IL-1β, IL-6, and TNF-α." (PMID 40231144, 2025). "It has been reported that ABMP increased NRF2 expression, alleviated gingival recession, reduced IL-1β and TNF-α levels, alveolar bone resorption, and osteoclasts number in periodontitis rat model." (PMID 40736688, 2025). "Selenium and selenoproteins contribute to the pathogenesis of chronic inflammatory diseases, including periodontitis, because of their role in immune regulation, cytokine secretion, immune cell activation, and the regulation of TNF-α produced by macrophages." (PMID 40325319, 2025). "In a ligature-induced periodontitis model, Nakao and research team members demonstrated that exosomes derived from TNF-α-preconditioned gingival mesenchymal stem cells (GMSCs) reduced the local inflammatory response." (PMID 40243684, 2025). "Like other studies, the current results demonstrated that the periodontitis group had a significantly higher TNF-α level in the GCF." (PMID 40426985, 2025). "In a rat periodontitis model, this formulation significantly reduced inflammatory cytokines IL-1β and TNF-α by about 65% and 60%, respectively, and increased M2 macrophage marker Arg-1 expression by approximately threefold." (PMID 41155020, 2025). "Given that TNF-α is a well-established pro-inflammatory cytokine involved in periodontal destruction, its association with TMAO levels and periodontitis status further supports the role of inflammatory-metabolic interactions in periodontal pathogenesis." (PMID 40131489, 2025). "In chronic periodontitis, IL-1 and the pro-inflammatory cytokine TNF are believed to regulate the spread of the inflammatory front into deeper areas of connective tissue, leading to attachment loss, osteoclast activation, and subsequent alveolar bone loss." (PMID 40572711, 2025). "Periodontitis is characterized by a sustained inflammatory response, with elevated levels of pro-inflammatory cytokines, such as interleukin-1β and tumor necrosis factor-α." (PMID 40693078, 2025). "Vaspin, a serine protease inhibitor, shows significantly elevated levels in obese patients with periodontitis, correlating with changes in inflammatory factors like TNF-α and IL-6." (PMID 41246338, 2025). "The proinflammatory cytokines and protease IL-1β, TNF-α, and matrix metalloproteinases (MMPs) are elevated in the saliva of periodontitis patients." (PMID 40418274, 2025). "As the results of immunohistochemistry showed, the pyroptosis-related protein levels of N-GSDMD, IL-1β, and IL-18, as well as the inflammatory factor TNF-α were significantly augmented in human periodontitis tissues compared with those in the healthy tissues." (PMID 40000642, 2025). "Difficulty chewing often stems from oral infections such as periodontitis, which release pro-inflammatory cytokines like IL-6 and TNF-α." (PMID 41181690, 2025). "Previous research has shown that certain biomarkers increase with the severity of periodontitis such as TNF-α and IL-1735." (PMID 39516276, 2025). "This dual modulation supports GLP-1RAs as a potential adjunctive anti-inflammatory therapy in periodontitis by suppressing cytokines such as IL-6, IL-1β, and TNF-α." (PMID 41328144, 2025). "IL-1β, IL-6, IL-17, IL-23, and TNF are well documented in periodontitis, having various roles in immune cell recruitment, pro-inflammatory activity, and periodontal tissue destruction." (PMID 41463036, 2025). "The concentrations of TNF-α were found to be 3.75 (pg/mL) for healthy sites, 3.43 (pg/mL) for gingivitis sites, and 4.47 (pg/mL) for periodontitis sites at baseline." (PMID 41303313, 2025).
periodontitis (continued). "Periodontal tissues of patients with periodontitis show increased production of inflammatory cytokines and elevated levels of inflammatory markers such as C-reactive protein, tumor necrosis factor-alpha, and interleukin-6 in the blood." (PMID 40076415, 2025). "One of the primary outcomes is the suppression of pro-inflammatory cytokines, such as TNF-α, IL-6, and NF-κB, which are downregulated, thereby reducing tissue destruction and limiting the progression of periodontitis." (PMID 40256760, 2025). "At baseline, TNF-α levels were significantly lower in the control group compared with all stages and grades of periodontitis (p < 0.05)." (PMID 41440349, 2025). "GCF TNF-α levels rise in inflammatory diseases like periodontitis, aiding in the degradation of inflamed periodontal tissues." (PMID 40426985, 2025). "According to the results of the post hoc Bonferroni test, the mean salivary and GCF levels of TNF-α and IL-1β in healthy individuals were significantly lower than those with periodontitis (P<0.05) and gingivitis (P<0.05)." (PMID 40265034, 2025). "The first section (1995–2011) concentrates on the impact of oral health particularly periodontitis on RA emphasizing key bacteria within the oral microbiome and their relationship with inflammatory factors such as TNF." (PMID 40740318, 2025). "Previous studies have shown elevated levels of IL-1β, TNF-α, and matrix metalloproteinase-9 in gingival tissues from ligature-induced periodontitis models." (PMID 40863312, 2025). "Cytokines, including TNF-α, CRP, IL-6, IL-17, IL-8 and IFN-γ, are associated with periodontitis and gestational diabetes mellitus." (PMID 41394354, 2025). "Key periodontitis-related mediators involved in AD pathogenesis are cathepsin B, gingipain, LPS, TNF, and IL-6." (PMID 40559320, 2025). "IF staining confirmed the enhanced expression of proinflammatory cytokines IL-1β and TNF-α in periodontitis tissues." (PMID 40307566, 2025). "Numerous studies have confirmed that individuals with periodontitis exhibit higher serum levels of inflammatory markers such as IL-1β, TNF-α, IL-17A, IL-6, and lower levels of the anti-inflammatory cytokine IL-10 compared to healthy controls." (PMID 40732209, 2025). "The local inflammation is represented by TNF-α, while the systemic inflammation that increases with the onset and progression of chronic periodontitis is represented by hs-CRP." (PMID 41466021, 2025). "A clinical study demonstrated that the expression of TNF-α is elevated in the gingival crevicular fluid of patients with chronic periodontitis." (PMID 39763707, 2025). "costus nanoparticles effectively reduced NF-κB and TNF-α expression in periodontitis, with a more pronounced effect observed on day 5 compared with day 2, suggesting its potential as a therapeutic agent in managing periodontal inflammation." (PMID 40774344, 2025). "In chronic periodontitis, IL‐1β and TNF‐α were considered to propagate inflammation into deeper connective tissues, promoting loss of attachment, osteoclast activation, and alveolar bone resorption." (PMID 41497811, 2025). "TNF-α, produced by macrophages in response to infections and tissue damage, is upregulated in inflamed gingival tissues during periodontitis, contributing to tissue degradation and enhancing the inflammatory response." (PMID 40283848, 2025). "This inflammatory response manifests through substantial elevations in interleukin-1 beta (IL-1β), tumor necrosis factor-α (TNF-α), and interleukin-6 (IL-6) in periodontitis patients." (PMID 40869031, 2025). "Patients with severe periodontitis exhibit significantly elevated levels of pro-inflammatory mediators—namely IL-1β, TNF-α, and IL-6—in both serum and saliva." (PMID 40869031, 2025). "Their results showed that after periodontitis treatment in hypertensive patients, the indices of pro-inflammatory cytokines TNF-α and IL-6 decreased and were within normal limits." (PMID 40002786, 2025).
periodontitis (continued). "Lipopolysaccharides and other byproducts from periodontitis elevate cerebral pro-inflammatory mediators (IL-1β, TNF-α, IL-6), which promote amyloid accumulation, leading to neurodegeneration and Alzheimer’s disease." (PMID 40433667, 2025). "The findings of this study align with established evidence, as elevated TNF-α levels in periodontitis patients reinforce its critical role in periodontal inflammation, connective tissue degradation, and alveolar bone resorption." (PMID 41440349, 2025). "Consistently, we found that the most notable difference in OPG production between GFs from healthy donors and periodontitis patients occurs after TNF stimulation and P. gingivalis infection." (PMID 41315835, 2025). "Specifically, the persistent inflammatory response in periodontitis leads to the activation of immune cells, which secrete a wide array of pro-inflammatory cytokines, such as TNF-α, IL-1β, and IL-6." (PMID 39987090, 2025). "In obese patients, adipose cells and macrophages within adipose tissue secrete TNF-α and IL-6; these adipocytokines play a pivotal role in the link between obesity and periodontitis." (PMID 41328144, 2025). "The role of inflammation in periodontitis is well-documented, with cytokines such as IL-6 and TNF-α playing central roles in disease progression." (PMID 40085302, 2025). "In the first part of the study, we examined the effect of adiponectin on the expression in periodontal ligament cells of mRNA of mediators involved in periodontitis pathogenesis (TNF-α, IL-1, IL-6, IL-8, IL-10, IL-17, IL-18)." (PMID 40282186, 2025). "After accounting for study quality and potential publication bias, meta-analyses conclude that TNF-α −308 genotyping alone has limited clinical utility as a predictive marker for common forms of periodontitis." (PMID 41300760, 2025). "In a highly inflammatory condition of periodontitis elevated TNF-α a pro-inflammatory cytokine, binds to IRS and impairs insulin signaling by serine phosphorylation of IRS-1 and reduces GLUT-4 expression." (PMID 40136728, 2025). "By eight weeks post-treatment, while some TNF-α correlations had weakened, their relationships with free fatty acids, the gingival bleeding index, and periodontitis grading strengthened." (PMID 41244040, 2025). "Salivary and serum TMAO levels and salivary TNF-α levels were significantly higher in the periodontitis group (p = 0.003, p = 0.004, and p = 0.031, respectively)." (PMID 40131489, 2025). "Studies have also shown that genistein significantly reduced the expression levels of TNF‐α, IL‐6, IL‐1β, and IL‐17a in the gingival tissue of periodontitis mice and reduced the damage of inflammatory factors to periodontal tissue." (PMID 40761494, 2025). "Group III exhibited the highest TNF-α levels, reflecting a compounded inflammatory effect of periodontitis and T2DM." (PMID 41280962, 2025). "Clinical studies indicate that serum leptin levels in periodontitis patients positively correlate with inflammatory markers like IL-6 and TNF-α." (PMID 41246338, 2025). "Promoting osteoclastogenesis and tissue destruction, these RANKL, TNF-α, and IL-1β regulators are well-known to induce periodontitis." (PMID 41050338, 2025). "In vivo studies have shown that periodontitis patients treated with anti-tumor necrosis factor-α significantly reduced IL-1β and IL-8 levels in gingival sulcus fluid and IL-8 levels in saliva." (PMID 40851867, 2025). "In rats with induced periodontitis, treatment with nootkatone significantly reduced the levels of inflammatory markers, such as IL-1β, IL-6, and TNF-α within the gingival tissue, showcasing its potential to protect against the degradation of alveolar bone." (PMID 40710159, 2025). "A key finding in our study was that ordinal regression analyses revealed a significant association between higher salivary TNF-α and TMAO levels and increased odds of having periodontitis, even after adjusting for age." (PMID 40131489, 2025).
periodontitis (continued). "TNFα was significantly elevated in t1DM patients with gingivitis (p < 0.0001) and periodontitis (p = 0.02), while IFNγ showed a significant increase only in healthy diabetic individuals (p = 0.02)." (PMID 41280935, 2025). "In an acute periodontitis model, this triterpenoid reduced tumor necrosis factor-alpha (TNF-alpha), MPO, and thiobarbituric acid reactive substances (TBARS)." (PMID 40559438, 2025). "Elevated TNF-α levels in saliva and serum have been consistently reported in patients with periodontitis, particularly in stage III and IV disease." (PMID 40131489, 2025). "After receiving therapy for periodontitis, TNF-α levels statistically significantly decreased (p = 0.000)." (PMID 40426985, 2025). "Systemically, periodontitis induces inflammation as evidenced by elevated serum IL-6 and TNF-α levels in periodontitis mice." (PMID 41040884, 2025). "TNF-α, a key pro-inflammatory cytokine, is significantly upregulated in periodontal tissues, serum, and gingival crevicular fluid of periodontitis patients, correlating with periodontitis activity." (PMID 41427424, 2025). "This study provides a comprehensive analysis of key inflammatory biomarkers (CRP, IL-1, IL-6, TNF-α) across all stages and grades of periodontitis, offering detailed insights into both systemic and local inflammatory responses." (PMID 41440349, 2025). "Significantly elevated serum levels of TNF-α and IL-6 were detected in the Experimental Periodontitis (EP) group, with significant differences compared to the Negative Control (NG) group." (PMID 40649395, 2025). "The inflammatory mediators released during periodontitis, including prostaglandins and tumor necrosis factor-α, can induce labor prematurely." (PMID 40283848, 2025). "From healthy to severe periodontitis, the expression of IL-1β, IL-6, IL-8, TNF and MMP-9 gradually increased, but the E–P interaction scores remained constant, suggesting a persistent epigenetic regulatory footprint." (PMID 40902506, 2025). "Increased IL-1β, IL-6, and TNF-α levels were also found in patients with periodontitis and AD suggesting the presence of overlapping mechanisms in the physiopathology of these diseases." (PMID 40736688, 2025). "Analyses of gingival tissues from healthy and periodontitis individuals demonstrated a statistically significant increase in the expressions of IL-1β, TNF-α and ZBP1 in infected tissues." (PMID 40307566, 2025). "In periodontitis, producing pro-inflammatory cytokines such as TNF-α, IL-1, IL-6, and IL-17 contributes to chronic inflammation, tissue degradation, and bone resorption." (PMID 40136728, 2025). "Both RA and periodontitis are driven by elevated levels of pro-inflammatory cytokines, such as TNF-α, IL-1, and IL-6, which promote tissue destruction in the joints and periodontium." (PMID 40066344, 2025). "Studies of neutrophils isolated from patients with chronic periodontitis report increased secretion of pro-inflammatory cytokines, i.e., IL-8, IL-6, TNF-α, and IL-1β." (PMID 39936030, 2025). "Elevated levels of GCF ghrelin and TNF-α were observed in periodontitis patients, with the highest levels seen in those with coexisting T2DM, suggesting a synergistic effect of systemic and local inflammation." (PMID 41280962, 2025). "The TNF-α levels were significantly higher in the periodontitis patients than the controls (p = 0.000) and decreased significantly after treatment (p = 0.000)." (PMID 40426985, 2025). "Cho reported that the administration of EGCG (200 mg/kg) through gavage for four weeks decreased the TNF-α and IL-6 levels in rats with induced periodontitis." (PMID 39452941, 2024). "The results revealed that the expression of NLRP3, IL‐1β, IL‐18, IL‐6, and TNF‐α was upregulated by F. nucleatum and its OMVs in rats with periodontitis." (PMID 39475060, 2024). "Based on previously published data, IL-1β, IL-6 and TNF-α were chosen, in order to mimic the inflammatory environment that can be found in periodontitis." (PMID 39252697, 2024).
periodontitis (continued). "The in vivo study used rat models with periodontitis to observe the TNF-α level in gingival crevicular fluid, the number of osteoclasts, and the expression of RANKL following the application of a 10% cocoa pod husk (Theobroma cacao L.) extract gel." (PMID 39630805, 2024). "Conversely, testosterone therapy in transgender males increases pro-inflammatory cytokines (e.g., TNF-α, IL-1α, CXCL1) and Th17 cells, potentially heightening inflammation in periodontal tissues and elevating periodontitis risk." (PMID 39917660, 2024). "The findings suggested that MBG did not have an impact on the expression of inflammatory genes (IL-1β, IL-6, iNOS and TNF-α) that were activated in the periodontitis microenvironment." (PMID 38449005, 2024). "Patients affected by gingivitis and periodontitis will have proinflammatory cytokines like TNF-α and IL-1β in their gingival tissue and gingival crevicular fluid." (PMID 38978754, 2024). "The mice with periodontitis had impaired cognitive function and increased amyloid-beta (Aβ) deposition in the brain, along with elevated pro-inflammatory cytokines (IL-1β and TNF-α)." (PMID 39044527, 2024). "Proinflammatory cytokines, such as IL-1α, IL-1β, IL-6, IL-8, TNF-α and TNF-β, are associated with osteoclastogenesis, a key process leading to clinical periodontitis outcomes and periodontitis-associated inflammatory diseases." (PMID 38396821, 2024). "In contrast, the injection of anandamide in rats with experimental periodontitis significantly reduced TNF-α and IL-1β levels compared with animals treated with saline and the antagonists, AM251 and AM630." (PMID 39065590, 2024). "A case–control study was carried out to estimate circulating levels of TNF‐α in the saliva and serum of patients with chronic periodontitis and periodontally healthy individuals." (PMID 39494478, 2024). "Elevated levels of TNF‐α, IL‐6, and CRP in the plasma of periodontitis patients are closely associated with obesity." (PMID 39675010, 2024). "Previous studies regarding serum levels of IL-1β and TNF-α in periodontitis presented diverging results and were based on small cohorts with different methods for protein assessment, making comparisons with our results challenging." (PMID 39101637, 2024). "Regarding TNF-α, ranges between 0.7 pg/mL and 14.6 pg/mL have been reported in diabetic patients with periodontitis in a meta-analysis." (PMID 39101637, 2024). "They concluded that an upsurge of pro-inflammatory interleukins i.e. interleukin-1 alpha (IL-1α), IL-1β, interleukin-12 (IL-12), and IL-6 along with TNF-α, found in periodontitis." (PMID 38196480, 2024). "Previous research has demonstrated that single nucleotide polymorphisms in the interleukin 1 gene, interleukin 10 gene, Fc gamma gene, and tumor necrosis factor-alpha gene are related to periodontitis in terms of genomic indicators of the disease." (PMID 38337597, 2024). "In this report, etanercept, a human dimeric fusion protein blocking TNF, was tested in ligature-induced experimental periodontitis in rats." (PMID 39253090, 2024). "It has been well documented that NF-kB activation, which is pivotal in periodontitis and cancer-related inflammation, induces the expressions of pro-inflammatory cytokines, including TNF-α, IL-1β, IL-6, and IL-8, in different cell types." (PMID 38612423, 2024). "Recent animal-based research revealed that orthodontic tooth movement exacerbates periodontitis by increasing IL-1 and TNF- levels." (PMID 38668024, 2024). "Among the main inflammatory mediators involved in periodontitis are IL-6 and TNF-α, although other authors also highlight the role of IL-1 and IL-8." (PMID 38396672, 2024). "TNF-α seems to be related to the quantity of macrophages in the surrounding tissues of the apical periodontitis, which creates more vascularisation and inflammation." (PMID 38893626, 2024).